AKR1C3 (aldo-keto reductase family 1 member C3)
Diseases named in the same sentence as AKR1C3 in open-access papers (continued):
Sharing a sentence is not in itself a finding about the gene and the disease.
cancer (continued). "This suggests that AKR1C3 is not a required gene for proliferation of these cancer cells." (PMID 25419901, 2014). "Since AKR1C3-mediated lipophilic hormone metabolism may function through a paracrine signaling, it may not require all cancer cells to express elevated levels of AKR1C3 to promote disease progression." (PMID 21134280, 2010). "Thus, for adjuvant therapy, AKR1C3 inhibitors do not necessarily have to be cytotoxic to cancer cells on their own; but instead would ideally prevent metabolism and improve the cytotoxic and antiproliferative activity of other anti-cancer drugs." (PMID 40905588, 2025). "Surprisingly, chalcone 25, a weak AKR1C3 inhibitor that could not be docked into the binding pocket of AKR1C3, had cytotoxic effects in almost the same concentration range as chemotherapeutic agents cisplatin and etoposide, conventionally used in cancer treatment." (PMID 35208174, 2022). "Importantly, no upregulation of AKR1C3 mRNA was detected upon ZAN treatment of HepG2 or KG1α cells, suggesting that ZAN does not affect systemic DAUN metabolism or influence the resistance of cancer cells to DAUN by promoting changes in AKR1C3 expression." (PMID 36297430, 2022).
endocrine diseases (5 papers, 2020 to 2023). "AKR1C3 has been confirmed to play a regulatory role in a variety of endocrine diseases." (PMID 33354250, 2020). "AKR1C3 is a member of the AKR superfamily and acts as a drug target in hormonal malignancies and endocrine disorders." (PMID 33493134, 2021). "AKR1C3, which belongs to the aldo-keto reductase superfamily acting as NADP(H) oxidoreductases, has been considered as the therapeutic target of multiple malignancies and endocrine diseases." (PMID 34568444, 2021).
AKR1C3 also shares sentences with these, for which no sentence is quoted: non-small cell lung carcinoma (4 papers); T-cell acute lymphoblastic leukemia (3); asthma (2); colorectal cancer (2); endometriosis (2); Gynecomastia (2); Hyperinsulinemia (2); acute leukemia (1); adenocarcinoma (1); allergic disease (1); anemia (1); B-cell acute lymphoblastic leukemia (1); B-cell non-Hodgkin lymphoma (1); Barrett esophagus (1); bipolar disorder (1); carcinoma in situ (1); carcinosarcoma (1); cardiovascular diseases (1); cholangiocarcinoma (1); cholestasis (1); choriocarcinoma (1); chronic lymphocytic leukemia (1); chronic myelogenous leukemia (1); chronic obstructive pulmonary disease (1); Disc Degeneration (1); endometrioid adenocarcinoma (1); endometritis (1); hematological malignancies (1); hypospadias (1); infection (1).
A further 11 diseases each share a sentence with AKR1C3 in 1 paper.